BCL2L1 (BCL2 like 1)
Diseases named in the same sentence as BCL2L1 in open-access papers (continued):
Sharing a sentence is not in itself a finding about the gene and the disease.
cardiomyopathy (3 papers, 2009 to 2024). A disease of the heart muscle or myocardium proper. "The results suggested genes (Pdk4, Igf1r, Lipe, Serpine1, and Bcl2l1) targeted cardiovascular diseases including cardiomyopathies, ventricular dysfunction, etc.." (PMID 38961143, 2024).
Cognitive impairment (3 papers, 2018 to 2019). Abnormal cognition is characterized by deficits in thinking, reasoning, or remembering. "In other words, defects in BCL2L1 could exert an adverse influence on the healthy aging (e.g. cognitive impairment)." (PMID 31666070, 2019).
colorectal adenocarcinoma (3 papers, 2015 to 2022). The most common type of colorectal carcinoma.
Myocardial fibrosis (3 papers, 2021 to 2024). "High-dose administration of chlorpromazine led to an elevated expression level of BCL2L1 and various cardiovascular disorders, such as arrhythmia and myocardial fibrosis." (PMID 33706714, 2021).
oropharyngeal carcinoma (3 papers, 2013 to 2022). Carcinoma, predominantly squamous cell, arising from the epithelial cells of the oropharynx. "High BCL2L1 expression is inversely correlated with the complete remission of oropharyngeal carcinoma patient treated with radical irradiation." (PMID 28423621, 2017).
pancreatic adenocarcinoma (3 papers, 2015 to 2021). "Among these genes, JUB, ERLIN1, FAM110B, MCM2 and BCL2L1 also had a diagnosis value for pancreatic adenocarcinoma." (PMID 29596435, 2018). "Finally, 8 differentially expressed genes (ERLIN1, HMGA2, FAM110B, EGFR, MCM2, BCL2L1, E2F1 and RAC1) were considered to be significantly negatively associated with survival (P < 0.05) time of pancreatic adenocarcinoma patients." (PMID 29596435, 2018). "Significantly, we also found that BCL2L1 had a diagnosis value for pancreatic adenocarcinoma." (PMID 29596435, 2018). "In this study, we found the role of BCL2L1 and E2F1 in the process of pancreatic adenocarcinoma, which was in line with previous researches." (PMID 29596435, 2018). "Herein, we found that BCL2L1, E2F1, RAC1 and STAT1 were expressed in pancreatic adenocarcinoma, which was consistent with previous reports." (PMID 29596435, 2018). "Significantly, we also found the roles of BCL2L1, E2F1 and RAC1 in tumor differentiation and survival prediction of pancreatic adenocarcinoma." (PMID 29596435, 2018). "According to the KEGG pathway analysis, we found that several tumor differentiation related genes (such as BCL2L1, E2F1, RAC1 and STAT1) were remarkably enriched in pancreatic adenocarcinoma signaling pathway." (PMID 29596435, 2018).
retinoblastoma (3 papers, 2014 to 2019). A malignant tumor that originates in the nuclear layer of the retina. "Our results demonstrated that STAT3 activation induced up-regulation of BCL2, BCL2L1, BIRC5, and MMP9 genes in retinoblastoma cells." (PMID 25359779, 2014). "Furthermore, target genes of STAT3 including BCL2, BCL2L1, BIRC5, and MMP9 are up-regulated in retinoblastoma cells compared to other retinal constituent cells." (PMID 25359779, 2014).
rheumatoid arthritis (3 papers, 2019 to 2023). A chronic, systemic autoimmune disorder characterized by inflammation in the synovial membranes and articular surfaces.
bladder tumor (2 papers, 2025). "Among them, 13 genes, including AHR, BCL2L1, CCND1, KRAS, SOX4, MYC, and E2F family genes, were previously reported to have increased expression in BC tissue, and their alterations, either through amplification or upregulation, are linked with bladder tumor initiation or progression." (PMID 40801146, 2025).
breast invasive carcinoma (2 papers, 2014 to 2024). "The analysis of the clinical stages of patients with breast invasive carcinoma indicated that the BAX, BCL2L1, CASP8, CASP9, RELA, and NFKBIA gene expression levels were higher in stages 3 and 4 for all BRCA patients, and in stage 4 for BRCA-LumA patients, than in other clinical stages." (PMID 38542508, 2024).
childhood cancer (2 papers, 2019 to 2025). "Employing predictive modeling approaches on a large set of childhood cancer cell lines with multiomics data features, we identified a potentially previously unreported cluster of CpG sites in the antiapoptotic BCL-xL/BCL2L1 gene, which predicted MCL1 inhibitor response." (PMID 39846250, 2025).
coronary heart disease (2 papers, 2016 to 2018). "Other smoking-related hub genes found to overlap with coronary heart disease-related expression profile include NEDD4L, BCL2L1 and CDKN1A." (PMID 26837704, 2016).
Hepatitis (2 papers, 2012 to 2022). Inflammation of the liver. "Meanwhile, we observed that in hepatitis-related HCC, patients with higher expression of BCL2L1, EGFR, ESR1, HNF4A, MAPK8, and PTEN, and lower expression of HDAC1 had a better clinical prognosis." (PMID 36133813, 2022).
Listeria infection (2 papers, 2011 to 2020). "Thus, lower mitochondrial BCL2L1 levels could also contribute to the increased mitochondrial fragmentation observed as a result of Listeria infection." (PMID 32019800, 2020).
periodontitis (2 papers, 2019 to 2022). An acute or chronic inflammatory process that affects the tissues that surround and support the teeth. "Studies have reported that anti-apoptotic BCL-2 and BCL2L1 (also known as BCLXL), and pro-apoptotic BID, BIM, and BAX may play roles in the pathogenesis of periodontitis." (PMID 35804353, 2022). "BCL2L1 was upregulated in four out of eight individuals without periodontitis after HmuY stimulation, while only one individual showed upregulation when the cells were cultured without stimulus." (PMID 31011284, 2019).
temporal lobe epilepsy (2 papers, 2020 to 2022). A localization-related (focal) form of epilepsy characterized by recurrent seizures that arise from foci within the temporal lobe, most commonly from its mesial aspect. "Moreover, effective inhibition of neuronal apoptosis provided a neuroprotective effect by the up-regulation of Bcl-2, Bcl2l1, Bdnf, Sox-2, and NeuroD1 genes in an animal model of temporal lobe epilepsy." (PMID 32982679, 2020).
cholesteatoma (1 paper, 2012). A pathologic process characterized by the proliferation of keratinizing squamous epithelium resulting in the accumulation of keratin and cells in the middle ear and/or mastoid. "Genes for anti-apoptotic proteins such as Bcl-xl (BCL2L1), A20 (TNFAIP3) and cIAP2 (BIRC3) show only a slightly higher expression in cholesteatoma (logFC 1.5–3)." (PMID 23285167, 2012). "Additionally, the message for anti-apoptotic proteins Bcl-xl (BCL2L1), A20 (TNFAIP3) and cIAP2 (BIRC3) show a slightly higher expression in cholesteatoma (logFC 1.5–3)." (PMID 23285167, 2012). "Real-time PCR of PI3, SPRR1B, LCN2 (lipocalin 2), MMP1, MMP9, MMP10, MMP12, SPP1, GJB2, Bcl-xl (BCL2L1), cIAP2 (BIRC3), S100A7A (koebnerisin), S100A9, SERPINB3, CEACAM6, KRT6B and SERPINB4 revealed that the expression levels of these proteins were higher in cholesteatoma than in external canal skin." (PMID 23285167, 2012).
delirium (1 paper, 2025). A disorder characterized by confusion; inattentiveness; disorientation; illusions; hallucinations; agitation; and in some instances autonomic nervous system overactivity. "The study indicates that the levels of INS, BCL2L1, and IL‐7 in CSF may be linked to the risk of delirium, with INS playing a pivotal role." (PMID 40922636, 2025). "In the PPI network analysis, INS, BCL2L1, and IL‐7 were identified as central nodes, indicating their potential significant role in the pathophysiology of delirium." (PMID 40922636, 2025). "Network analysis revealed several central nodes, including INS, BCL2L1, and IL‐7, which exhibited high connectivity, suggesting that these CSF proteins may play a central role in the pathophysiology of delirium." (PMID 40922636, 2025). "Our findings suggest that BCL2L1 expression in CSF may be negatively correlated with the occurrence of delirium." (PMID 40922636, 2025). "However, research on the involvement of BCL2L1 in delirium remains limited, highlighting the need for further investigation." (PMID 40922636, 2025). "Larger nodes like INS, IL7, and BCL2L1 suggest central roles in the delirium pathway." (PMID 40922636, 2025).
metastatic colorectal cancer (1 paper, 2021). "Among the gastrointestinal diseases targeted by both TYMS and BCL2L1, metastatic colorectal cancer ranked the first overall." (PMID 34141464, 2021).
muscle atrophy (1 paper, 2023). The loss of muscle tissue due to inactivity or disease. "Our molecular docking results showed that Aloin A had good binding interactions with HSP90AA1, AKT1, CTNNB1, BCL2L1, RELA, TNF, AKT3, the ranging from −7.9 to −8.9 kcal/mol, suggesting that Aloin A stably combined with these proteins for attenuating cancer related muscle atrophy." (PMID 38180061, 2023).
pneumoconiosis (1 paper, 2018). An occupational lung disorder caused by inhalation of dust particles. "Taken together, these results suggest that expression of let-7a-5p in pneumoconiosis is downregulated, while reduced let-7a-5p corresponds to high expression of BCL2L1 and poor survival of LA patients." (PMID 30497474, 2018).
retinal degeneration (1 paper, 2024). Degeneration of the retina. "Conversely, Bcl2l1 was not able to rescue photoreceptor survival in retinal degeneration models." (PMID 38994994, 2024).
vitiligo (1 paper, 2021). Generalized well circumscribed patches of leukoderma that are generally distributed over symmetric body locations and is due to autoimmune destruction of melanocytes. "The hub genes of vitiligo melanocytes include CDK1, HSP90AA1, AKT1, BCL2L1, HDAC2, HELLS, and KIF23." (PMID 33790887, 2021).
cancer (1,244 papers, 2003 to 2026). A tumor composed of atypical neoplastic, often pleomorphic cells that invade other tissues. "More specifically, BCL2L1 has nine SVs, and two of them, Bcl-xL and Bcl-xS, are commonly reported to be associated with cancer, being Bcl-xL an anti-apoptotic and oncogenic, while Bcl-xS acts as a pro-apoptotic tumor suppressor." (PMID 35086552, 2022). "For instance, BCL2L1 (BCLXL), as a transcript variant of anti-apoptotic protein, is highly expressed in carcinoma and resistant to apoptosis." (PMID 34195286, 2021). "Another apoptosis-related example is the BCL2L1 gene, where a switching from pro-apoptotic short isoform Bcl-xs to anti-apoptotic long splice variant Bcl-xl enable cancer to bypass programmed cell death." (PMID 31924844, 2020). "Bcl-xL, BCL2 like 1 (BCL2L1) encoded protein expressed in various malignant tumors and involved in facilitating resistance to chemotherapy." (PMID 29596435, 2018). "In this review, aberrant splicing events in cancer-associated genes, namely BCL2L1, FAS, HRAS, CD44, Cyclin D1, CASP2, TMPRSS2-ERG, FGFR2, VEGF, AR and KLF6, will be discussed." (PMID 30463359, 2018). "BCL2L1, due to its central role in apoptosis regulation, holds potential as a biomarker for diseases associated with apoptosis dysregulation, including certain cancers, albeit further research is necessary." (PMID 37845713, 2023). "SF3B1 blockade also exerted important molecular actions involving the splicing modulation of two clinically relevant SVs of BCL2L1 (Bcl-xL and Bcl-xS) associated with cancer -development and known to play an oncogenic role and a tumor suppressor actions, respectively." (PMID 35086552, 2022). "Moreover, cBioPortal analyses of the TCGA database 28 showed a significant co-occurrence (p=0.002) of genomic alterations of MLKL (mainly deep deletion and mutation) and BCL2L1 (BCL-x) (mainly amplification) in pan-cancer cohorts (32 studies, 10967 patients)." (PMID 33531997, 2021). "Furthermore, FLT1 of LUSC, ITGB1 of DLBC, MDM4, and CDKN1A of ACC, MAPK1, and ERBB3 of UCEC, FGFR1 of ESCA, and EREG and BCL2L1 of COAD have been strongly associated with patient survival in their respective cancers." (PMID 34079798, 2021). "Thus, ectopic expression of BCL2L1 rescues cancer cells from transcriptional repressor treatment and tumors with high levels of BCL2L1 or loss of BAK are resistant to MCL1 depletion." (PMID 32645016, 2020). "Furthermore, combination of BCLxL (BCL2L1-encoded) inhibitors and E7107 remarkably enhances cytotoxicity in cancer cells." (PMID 30635584, 2019). "We further validate that splicing modulator induces selective apoptosis in cancer cell lines with endogenous amplification and high expression of MCL1 or BCL2A1, and combination of splicing inhibition and BCLxL (encoded by BCL2L1) inhibition induces a synergistic cytotoxicity in cancer cells." (PMID 30635584, 2019). "Based on the evidence that cancer types with BCL2 and MCL1 amplification are more prone to inhibition of their encoded proteins, we hypothesized that cancers with a significant frequency of BCL2L1 amplification are more dependent on BCL-XL for survival." (PMID 26134786, 2015). "Analysis of BCL2L1, a key anti-apoptotic gene, showed elevated transcript levels were linked with significantly worse survival (p = 0.04), suggesting that tumors with heightened anti-apoptotic capacity may rapidly evade cancer therapies." (PMID 41514587, 2025). "OTX2 and other photoreceptor TFs, including NRL and CRX, drives anti-apoptotic factors like BCL2L1, linking this gene program to sustained cancer cell viability." (PMID 41198629, 2025). "During retinal development, OTX2 occupies a pivotal position in a photoreceptor gene hierarchy, including basic leucine zipper TFs NRL and CRX, both overexpressed in G3 MB, where they promote cancer survival via the anti-apoptotic factor BCL2L1." (PMID 41198629, 2025).
cancer (continued). "In summary, we demonstrated that the antiapoptotic protein MCL1 is essential for tumorigenesis of pHGGs and that BCL2L1 methylation acts as a potent pantumor predictor of AZD5991/S63845 response in several pediatric cancers, including but not limited to pHGGs." (PMID 39846250, 2025). "The BCL-X gene (or BCL2L1) regulates apoptosis and therefore has an extremely important role in cancer." (PMID 40190563, 2025). "We then examined the methylation status of 44 CpG sites mapping to the BCL2L1 locus in the Childhood Cancer Model Atlas cohort of 238 cell lines, which were subjected to Infinium methylation array (Illumina)." (PMID 39846250, 2025). "Similar to DNA methylation changes at promoter and CpG islands, nonisland regions such as shores are known to regulate gene expression in cancer, consistent with the correlation we found between the cg00300298 mark and BCL2L1 expression." (PMID 39846250, 2025). "BAK1 and BCL2L1 are key players in the regulation of apoptosis, a process often disrupted in cancer cells to evade cell death." (PMID 40869429, 2025). "The multifactorial marker ATP1A1/BCL2L1 improves the prediction of the response of cancer cells to CGs." (PMID 37904054, 2024). "AML was within the top three and the ninth highest ATP1A1/BCL2L1 expressing types of cancer, respectively, across 40 cancer cell lineages (Cancer Cell Line Encyclopedia, CCLE, portal and 33 tumor types (TCGA pan-cancer cohort)." (PMID 37904054, 2024). "BCL2 family genes are highly related to tumor development and prognosis among various cancers, and BCL2L1 is one of the most common amplified genes in cancer." (PMID 38316463, 2024). "A previous study reported that p19ARF reduced the formation of the protein complex between BECN1 and its negative regulator, BCL2L1, and then induced autophagy in cancer cells." (PMID 37169793, 2023). "BCL2L1 is particularly significant as a target in cancer therapy, where strategies are being developed to inhibit its anti-apoptotic function." (PMID 37845713, 2023). "Bcl2-L1 shares most of its functions and features with Bcl-xL and is known to be seen with abundant expression in a wide range of cancers." (PMID 37736508, 2023). "Genes associated with proliferation, and cell survival (BCL2L1), and tumor- cell growth (WT1) pathways for development of cancer were overexpressed, whereas molecules relevant to differentiation resistance (CSF1R) were underexpressed." (PMID 35246110, 2022). "BCL2-like 1 (Bcl-xl), a member of the anti-apoptotic protein family, inhibits chemotherapy-induced apoptosis in cancer cells." (PMID 35664698, 2022). "For example, aberrant splicing-mediated upregulation of BCL2-like 1 (BCL2L1) antiapoptotic isoform enhances the antiapoptotic ability of cancer." (PMID 35198444, 2022). "The overexpressed PARK7 protein interacts with the anti-apoptotic protein BCL2L1, increasing its mitochondrial localization, with effects in tumorigenesis, cancer cells proliferation, metastasis, recurrence and resistance to chemotherapy." (PMID 36500393, 2022). "Different results have reported the involvement of several members of the STAT family in the transcriptional regulation of the BCL2L1 gene, both in normal cells, such as hematopoietic and myoblast cells, and cancer cells." (PMID 33803452, 2021). "We then profiled the drug sensitivity atlas of BCL2L1-gained cancer and found that the genotype was multiresistant to various drugs with no significant sensitivity to any single agent in GDSC." (PMID 34351305, 2021). "As a dominant inhibitor of apoptosis, BCL2L1 is a central regulator of programmed cell death and an important target for anti-cancer drugs." (PMID 32777912, 2021). "It should be mentioned that SPTBN2 and BCL2L1 were upregulated together not only in OV but also in various types of cancers, which were validated by various types of tumors and normal samples at both the gene and protein levels." (PMID 34179092, 2021).